VSIG8 (V-set and immunoglobulin domain containing 8)
Tractability: Antibody: UniProt predicts a signal peptide or a membrane-spanning region.
Gene: Protein-coding gene on chromosome 1 (159,854,316 to 159,862,657, reverse strand). Ensembl gene ENSG00000243284.
Subcellular location: Membrane
Gene Ontology:
Molecular function: protein binding; RNA binding
Cellular component: membrane
Genetic constraint (gnomAD): Loss-of-function variants: 33 observed, 42.13 expected, observed/expected ratio (o/e) 0.78, 90% interval 0.59 to 1.05. The synonymous counts are far from expectation, so gnomAD's model fits this gene poorly and the ratio says little. Missense variants: 529 observed, 524.46 expected, observed/expected ratio (o/e) 1.01, 90% interval 0.94 to 1.08. Synonymous variants: 290 observed, 230.77 expected, observed/expected ratio (o/e) 1.26, 90% interval 1.14 to 1.38.
Homologues: Orthologues: chimpanzee VSIG8 (99% identical), macaque VSIG8 (98% identical), dog VSIG8 (89% identical), pig VSIG8 (88% identical), rat Vsig8 (88% identical), mouse Vsig8 (87% identical), rabbit VSIG8 (79% identical), guinea pig VSIG8 (79% identical), tropical clawed frog vsig8 (35% identical), zebrafish vsig8a (24% identical). Paralogues in human: CXADR (26% identical), CLMP (21% identical), IGSF11 (20% identical), ESAM (19% identical), GPA33 (17% identical), VSIG1 (17% identical), VSIG2 (15% identical), JAM3 (15% identical), F11R (14% identical), JAM2 (14% identical), MXRA8 (14% identical), MUC15 (10% identical), and 2 more.
Diseases named in the same sentence as VSIG8 in open-access papers:
VSIG8 is named in the same sentence as 6 diseases in open-access papers, as found by Europe PMC text mining. Sharing a sentence is not in itself a finding about the gene and the disease. The quoted sentences say what the papers report.
melanoma (1 paper, 2023). A malignant, usually aggressive tumor composed of atypical, neoplastic melanocytes. "A VSIG-8 inhibitor, L557-0155, which inhibits VISTA binding to VSIG-8 promoted cytokine production, including TNF-α and IFN-γ, as well as cell proliferation in peripheral blood mononuclear cells and suppressed melanoma growth." (PMID 36891296, 2023).
skin cancer (1 paper, 2024). "On the other hand, genes resulting from skin and lung metastases were already reported to be associated with diseases in the respective tissues, such as AGAP2 with skin cancer and VSIG8 with respiratory syndromes." (PMID 39409151, 2024).
cancer (3 papers, 2022 to 2024). A tumor composed of atypical neoplastic, often pleomorphic cells that invade other tissues. "Future studies generating VSIG8-deficient animals and blocking antibodies will further enhance our understanding of this potential immune checkpoint molecule in cancer immunotherapy." (PMID 36189222, 2022). "first reported the discovery of an interaction between VISTA and VSIG8,and suggested that agonism or antagonism of VSIG8 could be used for the treatment of cancer, autoimmunity, metabolic or inflammatory diseases." (PMID 39742253, 2024). "As putative binding partners for the well-known coinhibitory molecule VISTA, both VSIG3 and VSIG8 were able to negatively regulate T-cell responses and can be targeted in certain cancer types in which antitumor immunity is predominantly affected by the VISTA pathway." (PMID 36189222, 2022).
tumor (1 paper, 2024). "Identification of VISTA’s binding partner, VSIG8, on tumor cells, and its correlation with increased VISTA expression in human transcriptomic analyses suggests a potential therapeutic target." (PMID 39123357, 2024). "To investigate the molecular mechanisms underlying tumor-mediated T-cell inhibition, we examined whether MB tumor cells express either of VISTA’s binding partners implicated in T-cell suppression, VSIG3 and VSIG8." (PMID 39123357, 2024). "Both described tumor-expressed binding partners, VSIG3 and VSIG8, were expressed in vitro." (PMID 39123357, 2024).
VSIG8 also shares sentences with these, for which no sentence is quoted: autoimmune disorders (1 paper); breast tumor (1).